KRTAP12-1 (keratin associated protein 12-1)
Description:
In the hair cortex, hair keratin intermediate filaments are embedded in an interfilamentous matrix, consisting of hair keratin-associated proteins (KRTAP), which are essential for the formation of a rigid and resistant hair shaft through their extensive disulfide bond cross-linking with abundant cysteine residues of hair keratins. The matrix proteins include the high-sulfur and high-glycine-tyrosine keratins.
Synonyms: KAP12.1; KRTAP12.1
Tractability: No criterion of Open Targets' tractability assessment is met for any kind of drug.
Gene: Protein-coding gene on chromosome 21 (44,681,576 to 44,682,163, reverse strand). Ensembl gene ENSG00000187175.
Pathways (Reactome):
Developmental Biology: Keratinization
Gene Ontology:
Molecular function: protein binding
Cellular component: cytosol; keratin filament
Genetic constraint (gnomAD): Loss-of-function variants: 0 observed, 0.32 expected, observed/expected ratio (o/e) 0, 90% interval 0 to 1.86. That is too few expected variants to judge how well the gene tolerates losing a copy. Missense variants: 109 observed, 132 expected, observed/expected ratio (o/e) 0.83, 90% interval 0.71 to 0.97. Synonymous variants: 56 observed, 60.52 expected, observed/expected ratio (o/e) 0.93, 90% interval 0.75 to 1.16.
Homologues: Orthologues: chimpanzee KRTAP12-1 (93% identical), rat LOC120098854 (49% identical), mouse Krtap10-31 (48% identical), rat Krtap10-1 (48% identical), mouse Gm49918 (47% identical), mouse Krtap10-29 (47% identical), rat Krtap10-9 (47% identical), mouse Krtap10-21 (46% identical), mouse Krtap10-22 (46% identical), mouse Krtap10-25 (46% identical), mouse Krtap10-26 (46% identical), mouse Krtap10-27 (46% identical), and 14 more. Paralogues in human: KRTAP12-2 (90% identical), KRTAP12-3 (76% identical), KRTAP10-4 (47% identical), KRTAP10-9 (47% identical), KRTAP10-12 (46% identical), KRTAP16-1 (46% identical), KRTAP10-8 (45% identical), KRTAP10-11 (44% identical), KRTAP10-3 (44% identical), KRTAP10-7 (44% identical), KRTAP10-2 (43% identical), KRTAP10-5 (41% identical), and 35 more.